ANKRD1 (ankyrin repeat domain 1)
Diseases named in the same sentence as ANKRD1 in open-access papers (continued):
Sharing a sentence is not in itself a finding about the gene and the disease.
tumor (34 papers, 2016 to 2026). "At the protein level, ANKRD1 expression was significantly downregulated in TTN MUT allele tumour cells as well." (PMID 39748197, 2025). "Ankrd1 was found to be associated with tumor progression and drug resistance in some studies." (PMID 40362467, 2025). "TTN mutations also inhibit ANKRD1 expression via JUN disruption and enhance CD4/CD8 T‐cell infiltration, improving anti‐tumour immunity and outcomes." (PMID 39748197, 2025). "It was validated by Western blot analysis that ANKRD1 exhibited stable upregulation in TTN‐MUT tumours." (PMID 39748197, 2025). "The research primarily focused on examining how ANKRD1 influences the radiosensitivity of TTN mutant tumour cells." (PMID 39748197, 2025). "In a BALB/c subcutaneous tumour model, it was observed that overexpression of ANKRD1 resulted in an increase in the volume and weight of TTN‐MUT tumours in contrast with the control group." (PMID 39748197, 2025). "In an orthotopic model of SCC based on the intradermal injection of admixed SCC and fibroblasts, the lesions formed by SCC cells together with CAFs with silenced ANKRD1 were significantly smaller than those with control CAFs, with lesser tumor cell density." (PMID 38310103, 2024). "Previous research has suggested that the tumor-suppressive effect of ANKRD1 depends on the presence of p5316, which is the most frequently mutated gene in human cancer." (PMID 38438492, 2024). "Irrespectively, targeting ANKRD1 by gene silencing and stabilized ASOs was sufficient to suppress AP-1 activity in CAFs and reverse their tumor-enhancing properties, making it a target of likely translational significance." (PMID 38310103, 2024). "By upregulating Bcl2, a well-known anti-apoptotic protein, and decreasing the levels of GADD153, which can have complex roles in apoptosis regulation, Ankrd1 promotes tumor survival." (PMID 39420247, 2024). "Given its pivotal role in fostering tumor progression and conferring drug resistance, targeting Ankrd1 presents a compelling strategy for enhancing cancer treatment." (PMID 39420247, 2024). "Ankrd1 has emerged as a significant player in various cancer types, influencing tumor progression and therapeutic resistance through distinct molecular pathways." (PMID 39420247, 2024). "YAP promotes tumor progression by initiating the transcription of canonical YAP target genes (ANKRD1, CYR61, CTGF) through nuclear translocation." (PMID 38402174, 2024). "For example, in skin cancer models, interfering with Ankrd1 signaling in these fibroblasts has effectively reversed their tumor-promoting characteristics, suggesting a potential for broader application in other cancer types." (PMID 39420247, 2024). "ANKRD1 is a tumor-suppressive downstream gene of the Hippo pathway, downregulated in different human cancers." (PMID 34497759, 2021). "ANKRD1 promotes angiogenesis after acute wounding of mouse skin, but currently little is known about the potential role of ANKRD1 in tumor angiogenesis." (PMID 33614496, 2020). "q-PCR results showed that the YAP (Cyr61, Amotl2, and Ankrd1) and ERK1/2 target genes (c-Myc and ELK-1) were elevated in WISP2 deficient tumor samples." (PMID 32711570, 2020). "ANKRD1 was abundant in the tumour centre, while AMOTL2 and AXL were higher at periphery, where C3-positive microglia were also observed." (PMID 32404936, 2020). "The most strongly upregulated mRNA, ankyrin repeat protein 1 (ANKRD1), is a tumor suppressor gene that positively regulates apoptosis." (PMID 30814490, 2019). "In EGFR-mutant NSCLC patients, ANKRD1 was overexpressed in the tumor after the failure of EGFR-TKI therapy, especially after long-duration EGFR-TKI treatments." (PMID 30291293, 2018). "The main functions of the top genes in OSPC2 network were associated to sensitization to chemotherapy (CXCR4, ANKRD1, CYR61, EDN1, ATP1B1, ARHGEF1, RTF1), and tumor suppression (FGFR3, BCL11B)." (PMID 28482906, 2017).
tumor (continued). "Moreover, the YAP downstream genes CTGF, CYR61, and ANKRD1 were highly expressed in tumor ECs (CD31+ cells) compared with their NT counterparts." (PMID 40026246, 2025). "ANKRD1 has been identified as an anti-inflammatory factor and is related to tumor drug resistance." (PMID 38438492, 2024). "Based on these findings, we speculate that decreasing ANKRD1 expression or function may be a potential strategy to mitigate tumor drug resistance." (PMID 38438492, 2024). "Furthermore, the expression of the Hippo pathway target genes Ankrd1, Cyr61, Amoltl2, and Taz) was significantly reduced in Gp130FF; Yap1KD tumor organoids." (PMID 37957015, 2024). "Using the CTRP database, we discovered that ANKRD1 may influence the half-maximal inhibitory concentration (IC50) of several anti-tumor drugs." (PMID 38438492, 2024). "A YAP1 target gene that displays a tumor suppressive effect is ANKRD1." (PMID 29179447, 2017). "Our results suggest that ANKRD1 may act as a tumor suppressive target of the Hippo signaling pathway." (PMID 29179447, 2017). "Wnt/β-Catenin also regulates Ankrd1 expression in mouse tumours." (PMID 27790377, 2016). "However, Ankrd1 has also been reported to function as a tumor suppressor." (PMID 40362467, 2025). "Additionally, we speculated that ANKRD1 may play a role in tumor drug resistance via inflammatory and immune-related pathways." (PMID 38438492, 2024). "This suggests that ANKRD1 may have a significant role in tumor development and progression." (PMID 38438492, 2024). "Four tumor-related genes (NR4A3, CD74, PPP1R3C, and ANKRD1) with high differential expression were selected, and the GeneMANIA database was used to generate a protein–protein interaction (PPI) network diagram." (PMID 39474111, 2024). "Overexpression of Ankrd1 or suppression of miR-3614-5p counteracts the effects of RGMB-AS1 silencing, promoting tumor proliferation and invasion." (PMID 39420247, 2024). "Using immunofluorescence, we found that YAP1 downstream effectors identified in mRNA analysis, ANKRD1, AMOTL2 and AXL were increased in LATS1/2 cKO tumours." (PMID 32404936, 2020). "ANKRD1 is a member of the ankyrin repeat protein family [NCBI, Gene, NG_023227.1], and has been reported to be a tumor suppressor gene that positively regulates apoptosis." (PMID 30814490, 2019). "LOC80078 and LOC101930114 were the most significantly up- and down-regulated DELs; EEF1A2 and ANKRD1 were the most significantly up- and down-regulated DEMs in TNM I stage LUAD tissues compared to paired non-tumor tissues." (PMID 28881680, 2017). "A comparison of these with the 683 KPTN tumor–upregulated genes revealed 130 consistently upregulated genes, including ECM components (COL4A1, COL4A2, COL12A1, VCAN, etc.)and YAP targets (ANKRD1, AXL, CYR61, F3)." (PMID 41480763, 2026). "Moreover, HUVECs cocultured with CRC patient–derived monocytes exhibited enhanced migratory ability, tube-forming capacity, and tumor cell transendothelial migratory ability and increased expression levels of YAP downstream genes CTGF, CYR61, and ANKRD1." (PMID 40026246, 2025). "Thus, targeting ANKRD1 by ASOs can be a feasible approach to revert CAF activation and suppress their tumor-enhancing properties." (PMID 38310103, 2024). "In our LATS1/2 cKO mouse model, although some of the tumour markers were highly present in the centre of the tumour mass, e.g., ANKRD1, Vimentin, CK18, nestin and Ki67, some were localised towards the edges of the tumour, e.g., HOPX, AMOTL2, AXL and microglial marker C3." (PMID 32404936, 2020).
tumor (continued). "The expression levels of ADARB1 (P<0.01), ADRB2 (P<0.05) and ANKRD1 (P<0.05) were significantly down-regulated in stage I LUAD tissues; COL1A1 (P<0.05) and MMP13 (P<0.05) were significantly up-regulated in stage I LUAD tissues compared with adjacent non-tumor tissues." (PMID 28881680, 2017).
cancer (33 papers, 2012 to 2025). A tumor composed of atypical neoplastic, often pleomorphic cells that invade other tissues. "The results indicated that Ankrd1 is associated with the progression of ccRCC, as in the case of other cancers." (PMID 40362467, 2025). "ANKRD1 localizes to the nucleus and is a component a complex called Titin that carries cancer-associated “driver” mutations." (PMID 38402174, 2024). "Specifically, the disruption of Ankrd1 interactions within the microenvironment of tumors, such as in cancer-associated fibroblasts, has demonstrated significant potential." (PMID 39420247, 2024). "Immune cell infiltration analysis revealed a strong association between ANKRD1 expression and cancer-associated fibroblast and macrophage, particularly M2 macrophage." (PMID 38438492, 2024). "ANKRD1 expression showed significant correlations with immune cell infiltration (including cancer-associated fibroblast and M2 macrophages), immune checkpoints, TMB, MSI, and MMR." (PMID 38438492, 2024). "The negative regulation of apoptosis in the cancer cells described is associated with increased expression of the ANKRD1 gene." (PMID 37511632, 2023). "In previous reports on other cancers, Ankrd1 was found to be associated with EMT." (PMID 40362467, 2025). "ANKRD1 shows potential as a diagnostic or prognostic biomarker in pan-cancer, especially COAD." (PMID 38438492, 2024). "Furthermore, results from large number of patients with CRC suggested that high expression of YAP1, TEA domain family member 2(TEAD2) and YAP1 target genes cysteine-rich angiogenic inducer 61 (CYR61) and ankyrin repeat domain 1 (ANKRD1) were associated with a high risk of cancer relapse." (PMID 32503256, 2020). "The STRN4 palmitoylation reduced YAP phosphorylation, promoted nuclear translocation of YAP and activated downstream Hippo pathway transcriptional targets—including CCN1, CCN2 and ANKRD1—thereby driving cancer cell migration." (PMID 40903842, 2025). "Both in vitro and in vivo functional studies demonstrated the essential role of ANKRD1 in cancer cell migration and invasion." (PMID 39409926, 2024). "Here, we delve deeper into the specific functions and implications of Ankrd1 in different cancers, illustrating its pervasive influence on disease outcomes." (PMID 39420247, 2024). "Since we found that ANKRD1 contributes to cancer cell migration and invasion, we further investigated its role by performing in vivo mouse experiments." (PMID 39409926, 2024). "To evaluate the expression specificity of ANKRD1 in pan-cancer, we conducted a receiver-operating characteristic (ROC) curve analysis." (PMID 38438492, 2024). "Previous studies found high level of DNA methylation of Ankrd1 in several human cancer cell lines, such as A427, LNCaP, MCF7, MeWo, and BxPC-3 cells." (PMID 39420247, 2024). "While the research on Ankrd1’s involvement in cancer progression and resistance to therapy offers promising insights, several critical limitations remain that must be addressed to fully leverage its potential as a therapeutic target." (PMID 39420247, 2024). "In summary, ANKRD1 represents a potential prognostic biomarker and therapeutic target in human cancers, particularly in COAD." (PMID 38438492, 2024). "Even in vivo, in an orthotopic model of tumorigenesis, SCC cells admixed with CAFs pre-treated with ANKRD1-ASOs produced smaller tumors than when admixed with control CAFs, with lesser cancer cell density." (PMID 38310103, 2024). "We find that the ANKRD1 gene is specifically expressed and upregulated in CAFs of various cancer types, is a direct target of AR suppression, and is both required and sufficient for CAF activation." (PMID 38310103, 2024).
cancer (continued). "Ankrd1 enhances cell survival through its anti-apoptotic functions, thereby allowing cancer cells to evade the cytotoxic effects of these drugs." (PMID 39420247, 2024). "ANKRD1 exhibited distinct expression patterns in pan-cancer and was found to be abnormally expressed in 19 types of tumors based on TCGA + GTEx databases (P < 0.05)." (PMID 38438492, 2024). "Since EMT is crucial for invasion and metastasis, it is interesting to explore the role of ANKRD1 in cancer invasion." (PMID 39409926, 2024). "In vitro studies revealed significant upregulation of ANKRD1 at both the transcriptional and translational level in highly metastatic cancer cells." (PMID 39409926, 2024). "This review consolidates current knowledge on Ankrd1’s functions in myocardium and skeletal muscle development, neurogenesis, cancer, bone formation, angiogenesis, wound healing, fibrosis, apoptosis, inflammation, and infection." (PMID 39420247, 2024). "Upregulation of other cancer-associated genes in MPOSE – such as Ccnd1, Btc, Ankrd1, Oraov1, Cd44 and Ifitm3 – as well as possible DNA mutations or fusions, may also contribute to tumorigenic differences and warrant further investigation." (PMID 40642792, 2025). "Dysregulation of ANKRD1 expression in pan-cancer involves DNA methylation and microRNA regulation." (PMID 38438492, 2024). "Therefore, to truly ascertain the viability of targeting Ankrd1 in cancer treatment, it is essential to conduct more comprehensive in vivo studies and to initiate large-scale clinical trials that encompass a broad demographic spectrum." (PMID 39420247, 2024). "Thus, Ankrd1 plays a critical role in OSA by modulating cancer cell dynamics and represents a potential therapeutic target." (PMID 39420247, 2024). "Our findings indicate that ANKRD1 expression is dysregulated in pan-cancer." (PMID 38438492, 2024). "Hence, the role of ANKRD1 in pan-cancer is likely to be complex and warrants further investigation, particularly in diverse racial or ethnic populations." (PMID 38438492, 2024). "We further studied how ANKRD1 affects cancer migration and invasion." (PMID 39409926, 2024). "As with CAFs in isolation, quantification by ImageJ analysis showed that ANKRD1 silencing causes no significant changes in fibroblast density as opposed to cancer cells." (PMID 38310103, 2024). "ANKRD1 thus represents a target for fibroblast-directed therapy in cancer and potentially beyond." (PMID 38310103, 2024). "Furthermore, ANKRD1 mRNA levels were found to possess prognostic value in predicting overall survival (OS) for 14 types of cancers." (PMID 38438492, 2024). "Moreover, the expression of ANKRD1 positively correlated with immune checkpoint genes in most cancers, except TGCT." (PMID 38438492, 2024). "However, there have been no studies investigating the prognostic value and molecular function of ANKRD1 in pan-cancer." (PMID 38438492, 2024). "Therefore, the role of ANKRD1 in different cancers should be analyzed according to the actual situation of cancer." (PMID 37702613, 2023). "ANKRD1 might be closely correlated with the drug-tolerant subpopulation of cancer cells which is commonly involved in the drug resistance to EGFR-TKIs." (PMID 30291293, 2018). "Further analysis revealed that ANKRD1 is epigenetically inactivated in human cancer." (PMID 29179447, 2017). "Thus we investigated the promoter methylation of ANKRD1 in these cancer cells by combined bisulfite restriction analysis." (PMID 29179447, 2017). "To assess whether suppression of ANKRD1 expression in CAFs by this approach exerts long term consequences on neighboring cancer cells, we pre-treated CAFs for 48 h with either ANKRD1-specific or scrambled ASOs followed by coculturing with SCC cells for seven days." (PMID 38310103, 2024). "Therefore, further research is warranted to confirm the findings of ANKRD1 in pan-cancer." (PMID 38438492, 2024).
cancer (continued). "Reflecting the biochemical effects, treatment with T-5224 suppressed expression of CAF effector genes in the ANKRD1 overexpressing cells as well as in CAFs and, in co-culture assays, was sufficient to counteract the growth-enhancing effects exerted by these cells on neighboring cancer cells." (PMID 38310103, 2024). "Moreover, an emerging role for Ankrd2-homolog Ankrd1 in cancer development has been proposed." (PMID 33419058, 2021). "In addition, the correlation between WNT5A and the CTGF/ANKRD1 signature as a readout for YAP/TEAD activity might be correlated with cancer progression in both TGCT and PAAD." (PMID 33643710, 2021). "However, ANKRD1 expression was very low in several cancer cell lines (e.g. LNCaP, MCF7 and MeWo)." (PMID 29179447, 2017). "Therefore, we speculate that ANKRD1 may play an important role in cancer etiology." (PMID 38438492, 2024). "The findings are of translational significance, as targeting ANKRD1 by genetic or chemical tools reverts CAF activation and inhibits cancer/stromal cell expansion." (PMID 38310103, 2024). "We also demonstrated that ANKRD1 is upstream of NF-κB-MAGE-A6 and plays a role in cancer metastasis." (PMID 39409926, 2024). "KIRREL1 knockout led to a significant increase in the expression of YAP target genes CTGF, CYR61, and ANKRD1, suggesting that KIRREL1 restricts YAP/TAZ activity in these cancer cell lines." (PMID 35177623, 2022). "Consistent with the observed IAG933 activity in a subset of Hippo-unaltered cell lines, additional profiling on 263 cancer cell lines revealed higher sensitivity in cells that display high basal TEAD activity, as determined by a four-gene (CCN1, CCN2, ANKRD1 and AMOTL2) transcriptional signature." (PMID 38565920, 2024). "To explore the impact of ANKRD1 on chemotherapy or targeted therapy, we collected data from the Cancer Therapeutics Response Portal (CTRP) database, which includes drug sensitivity and ANKRD1 mRNA expression information from various cancer cell lines." (PMID 38438492, 2024). "Immunofluorescence (IF) analysis of skin SCC samples further demonstrated elevated ANKRD1 expression in CAFs versus fibroblasts of flanking skin with no expression in cancer cells." (PMID 38310103, 2024). "ANKRD1 shows increased expression during oxidative stress in bovine GC and DDIT4 (also called REDD1) is a regulator of caspase-2 (via the ATF4-dependent pathway) in human cancer cells." (PMID 36737804, 2023). "Interestingly, GO and KEGG pathway analysis of ANKRD1 in HNSC did not enrich any cancer-related signaling pathways, but related to myocardial-related functions or pathways." (PMID 38438492, 2024). "However, the role of ANKRD1 in pan-cancer has not been thoroughly investigated." (PMID 38438492, 2024). "Interestingly, high expression of ANKRD1 did not demonstrate a protective effect in pan-cancer." (PMID 38438492, 2024). "In 769-P, Ankrd1 expression was slightly reduced by XMD17-109 but not by XMD8-92, which indicated that at least in 786-O, Ankrd1 expression is regulated not only via the Hippo pathway but also via another pathway specific to cancer cells." (PMID 40362467, 2025).